IL10 (interleukin 10)
Diseases named in the same sentence as IL10 in open-access papers (continued):
Sharing a sentence is not in itself a finding about the gene and the disease.
tumor (continued). "IL-10 deficiency releases pro-inflammatory cytokines, suppressing anti-tumor immunity and promoting growth, while high IL-10 levels may enhance tumor-specific immunity." (PMID 40443668, 2025). "Additionally, they suppress anti-tumor immune responses by producing interleukin-10 (IL-10) and transforming growth factor-β (TGF-β), inhibiting T-cell activation and promoting regulatory T-cell (Treg) recruitment." (PMID 41142306, 2025). "Additionally, regulatory T cells (Tregs), by secreting TGF-β and IL-10, promote immune tolerance, facilitating a tumor-friendly microenvironment." (PMID 40004489, 2025). "In summary, the pro-tumor effects of IgA include: 1) IgA inhibits CD8+ T cell function through the expression of PD-L1 and IL-10 and activates inflammatory pathways; 2) Interaction with CAFs enhances immunosuppressive properties and weakens anti-tumor responses." (PMID 41357192, 2025). "Moreover, TAMs can inhibit the anti-tumor function of immune system by up-regulating the expression of immunosuppressive cytokines such as IL-10 and TGF-β, while down-regulating the expression of immune activating cytokines such as IL-12." (PMID 38976211, 2025). "For instance, certain fungal compounds may induce tumor cells to secrete immunosuppressive cytokines, such as IL-10 and TGF-β." (PMID 40557321, 2025). "Furthermore, IL-10 promotes the expansion and function of Tregs, which are key players in maintaining immune tolerance and suppressing anti-tumor immunity." (PMID 40739089, 2025). "The M2 phenotypes are, on the other hand, stimulated by IL-4 and IL-13 to produce and secrete growth factors such as VEGF and TGF-β, MMPs and other cytokines such as IL-10, IL-13 and IL-4, and in that way contribute to increased proliferation of tumor cells and angiogenesis in the TME." (PMID 40376304, 2025). "IL-10, on the one hand, can enhance the maintenance of the PD-L1/PD-1 axis, thereby promoting immune escape of tumor cells, and on the other hand, IL-10 induces up-regulation of PD-L1 expression in monocytes, thereby weakening CD8+ T cell-mediated immune surveillance." (PMID 40557160, 2025). "Additionally, XPO1 inhibition can impair the production of the immunosuppressive cytokine IL-10, potentially preventing the inhibition of an ongoing anti-tumour immune response." (PMID 40291981, 2025). "If tumor signals downregulate these enzymes, TAMs might overproduce inhibitory cytokines like IL-10." (PMID 40358164, 2025). "Moreover, Arg1 expression in TAMs is sustained by a complex tumor milieu, including IL-4/IL-13, IL-10, TGF-β, lactic acid, hypoxia, and metabolic crosstalk, which is not fully recapitulated by IL-4 alone in vitro." (PMID 41465516, 2025). "Specifically, immune-suppressive components of the TIME—such as regulatory T cells (Tregs), tumor-associated macrophages (TAMs), and elevated levels of cytokines like TGF-β and IL-10—may induce metabolic reprogramming that favors LINC02802 expression." (PMID 40860186, 2025). "In this regard, we may speculate that the moderate increase in Foxp3 and PD-1 expression in colon tissue of CNF1 + DSS-treated mice may be an early consequence of the immune-suppressive and tumor-promoting modulation exerted by IL-10 and neutrophils." (PMID 39876002, 2025). "This holds significance as IL-10 has a profound influence on promoting tumor development." (PMID 41017127, 2025). "In addition, Pdgfc, which promotes angiogenesis and the immunosuppressive cytokine Interleukin 10 (Il10), that contributes to tumor immune evasion, were upregulated in Mir34aΔMye macrophages, particularly in the Mrc1+ subtype." (PMID 39425000, 2025). "Furthermore, we also analyzed the expression of TNF‐α, IL‐6, and IL‐10 genes in tumor tissues, which were consistent with the ELISA results, with the most significant changes observed in the CB‐AKK combined group improved by 19 times." (PMID 40497373, 2025).
tumor (continued). "By disrupting the regulatory effects of IL-10 and IL-6, it may be possible to enhance anti-tumor immunity and improve the efficacy of existing cancer therapies." (PMID 41583453, 2025). "Compared to the oe‐NC+M2pep‐Cs NPs/Plerixafor group, the mRNA levels of CD80, IL‐1β, and IL‐6 were significantly downregulated, and the mRNA levels of CD206 and IL‐10 were significantly upregulated in the tumor tissues of mice in the oe‐CXCR4+M2pep‐Cs NPs/Plerixafor group." (PMID 40536774, 2025). "Alternatively, some therapeutic strategies seek to harness the anti-tumor potential of IL-10 by delivering it in a controlled manner or in combination with other immune-stimulating agents to selectively enhance its beneficial effects while minimizing its immunosuppressive impact." (PMID 40739089, 2025). "While this may help prevent tissue damage from chronic inflammation, IL-10 can also facilitate tumor growth by suppressing immune surveillance." (PMID 40563651, 2025). "Moreover, current research primarily involves correlation analysis and lacks blocking experiments on IL-10 and TGF-β1 to directly establish their causal relationship with the tumor immune microenvironment and treatment outcomes." (PMID 41438510, 2025). "For CLL, this suggests that transient IL‐10 blockade may counteract tumor‐driven suppression, while preserving long‐term IL‐10R signaling required to maintain progenitor‐like CD8+ T cells." (PMID 41368078, 2025). "Several other interleukins, such as IL-6, IL-10, IL-12, and IL-17, have been implicated in the pathogenesis of HPV infection and cervical cancer which may play important roles in the tumor microenvironment." (PMID 41408300, 2025). "Impaired by factors like TGF-β and IL-10; less effective in controlling tumor growth." (PMID 40563466, 2025). "Specifically, Tregs can impair the anti-tumor function of effector T cells through direct contact or the secretion of inhibitory cytokines such as IL-10 and TGF-β, while M2-type macrophages promote angiogenesis and suppress T-cell activity by releasing mediators like VEGF and arginase." (PMID 41583466, 2025). "Moreover, SEC61G reshaped the tumor immune microenvironment by promoting microglial M2 polarization and suppressing M1 polarization, accompanied by increased secretion of IL-6 and IL-10." (PMID 39990664, 2025). "FcγRIIlow/- B cells can secrete IL-10 to inhibit the anti-tumor response of cytotoxic T cells." (PMID 39744696, 2025). "Furthermore, M2-polarization of macrophages is promoted by growth factors, such as the colony-stimulating factor (CSF-1), and cytokines, like IL-4, IL-13 and IL-10, released by cells in the tumor-microenvironment." (PMID 39425000, 2025). "Together with TRKA-dependent induction of IL-10 in human macrophages exposed to tumor-derived danger signals, these data support a model in which NGF promotes immune suppressive myeloid states that hinder cytotoxic lymphocyte activity within mineralized tumor beds." (PMID 41567220, 2025). "Through the downstream JAK‐STAT signaling pathway, METTL3 lactylation promotes the expression of immunosuppressive effector molecules such as interleukin (IL‐6, IL‐10, and inducible nitric oxide synthase), ultimately promoting tumor immune evasion and accelerating tumor growth and proliferation." (PMID 40443721, 2025). "We found that Treg cells expressing Il10, Tigit, and Tnfrsf were in proximity to tumor cells." (PMID 40457060, 2025). "In addition, cisplatin can enhance the infiltration and activation of DCs by upregulating IL-10, thus further activating a robust anti-tumor immune response and improving treatment outcomes." (PMID 39757995, 2025). "Furthermore, certain antitumor factors, including IL-2, IL-10, and IL-17A, mitigate tumor immune evasion, contributing to improved outcomes." (PMID 40313970, 2025).
tumor (continued). "The tumor actively suppresses immune activation through mechanisms such as the secretion of immunosuppressive cytokines (e.g., IL-10, TGF-β), the recruitment of regulatory T cells (Tregs) and myeloid-derived suppressor cells (MDSCs), and the overexpression of immune checkpoint molecules like PD-L1." (PMID 40143152, 2025). "Neutralizing exosomal miR-145 or inhibiting IL-10 signaling can reduce tumor growth in such models." (PMID 40358164, 2025). "It has been reported that IL-10 enhances the inhibitory effect of OVV on tumor cells in mice." (PMID 40469178, 2025). "It has been demonstrated that in the tumor microenvironment, M1 macrophages may be polarized to M2 macrophages by certain factors secreted by tumor cells, including IL-10 and TGF-β, which consequently facilitate tumor growth and metastasis." (PMID 40352921, 2025). "However, during tumor progression, these liver-resident cells can also contribute to immune tolerance by secreting the anti-inflammatory cytokines such as IL-10 and transforming growth factor-beta (TGF-β), and expressing PD-L1, which hinders T-cell activation." (PMID 41002563, 2025). "Elevated numbers of regulatory T (TREG) cells, Myeloid-derived suppressor cells (MDSCs), tumor-associated macrophages (TAMs), and the presence of inhibitory cytokines such as transforming growth factor-β (TGF-β) and interleukin 10 (IL-10) collectively suppress T cell activation and persistence." (PMID 41470115, 2025). "Tumor cells themselves can induce surrounding stromal cells to secrete IL-10." (PMID 41007766, 2025). "In the immunogenic model RLS40, DNase I had anti-tumor, antimetastatic, and immunostimulatory effects and significantly modified the neutrophil profile by decreasing the expression of the immunosuppressive markers (Il10, Ccl17) and increasing the expression of the anti-tumor markers (PD-L1, FAS)." (PMID 40867260, 2025). "The effect of S3QEL 1.2 on tumor growth may therefore be a combination of a dual effect on tumor cell proliferation and inhibition of IL-10 to promote antitumor immunity." (PMID 39841829, 2025). "In addition, IL‐10 overexpression in tumor cells was induced by TGF‐β, which subsequently activated Th2 cells while suppressing Th1 immune activity." (PMID 39927632, 2025). "Highlighting the controversial role of both IL-10 and IL-17 in tumor metastasis; in the CRC context, it has been reported that secretion of CTSK stimulated by the gut microbiota, in turn promotes IL10 and IL17 release from M2 TAMs, promoting CRC invasion and metastasis through NF-κB pathway." (PMID 40917756, 2025). "Depending on their subtype, TAMs can produce either pro-inflammatory cytokines (e.g., IL-1β and IL-6) or anti-inflammatory cytokines (e.g., IL-4 and IL-10), thereby modulating the cytokine profile and shifting the tumor microenvironment toward either tumor suppression or tumor promotion." (PMID 40308575, 2025). "Therefore, IL-10 exhibits complex pleiotropic effects on anti-tumour immunity, with the potential to either enhance or reduce tumour immunogenicity." (PMID 39325360, 2025). "The underlying mechanism may involve tumor-associated DCs secreting immunosuppressive factors such as IL-10 and TGF-β1, which inhibit T cell activation and promote tumor growth, suggesting that DC dysfunction may be a key component of immune evasion." (PMID 40755754, 2025). "This may be related to the increased release of cytokines such as IL-10 and IL-6 in tumor microenvironment that can promote BTLA expression after PD-1/PD-L1 blockade." (PMID 40463377, 2025). "However, tumor cells often secrete excessive amounts of IL-10, thereby leveraging its function to dampen effective anti-tumor immunity." (PMID 39930476, 2025). "Manipulating DC-SIGN+ cells may aid in enhancing anti-tumor immunity or responses against chronic infections by reducing their IL-10 output to promote more robust effector T cell responses." (PMID 40076949, 2025).
tumor (continued). "Furthermore, B cell-derived GABA induces monocyte differentiation into M2 macrophages, which secrete IL-10 to support tumor survival." (PMID 41246318, 2025). "Of note, supplementation of microbe-derived butyrate substantially suppresses PD-L1 and IL-10 expression as well as tumor growth in mouse xenografts, concomitant with down-regulation of immunosuppressive pathways (e.g., NF-κB and STAT3) and pro-tumorigenic factors (e.g., VEGF and GDF-15)." (PMID 40357361, 2025). "Additionally, M2d-polarized macrophages stimulated by adenosine, IL-6 and tumor cells secrete proteases (such as MMP-2), cytokines (such as VEGF) and anti-inflammatory factors (such as TGF-β and IL-10) to promote angiogenesis and tumor immunosuppression." (PMID 40703527, 2025). "Blocking IL-10 boosts anti-tumor immunity, and IL-10 may upregulate KPNA2, promoting tumor growth; KPNA2 knockout impairs these processes." (PMID 40443668, 2025). "The immunosuppressive TME, characterized by regulatory T cells (Tregs), myeloid-derived suppressor cells (MDSCs), and tumor-associated macrophages (TAMs) secreting cytokines like TGF-β and IL-10, further suppresses T cell responses and promotes tumor progression." (PMID 40165974, 2025). "In addition, elevated expressions of antitumor factors such as IFN-γ and TNF-a, as well as decreased expression of tumor promoting factors such as IL-10 and TGF-β were detected in the tumor tissues of SEMA7A-knockdown LLC tumor-bearing mice." (PMID 41019072, 2025). "This suggests that early IL-10 elevation may predict a tumor-driven immunosuppressive feedback mechanism, which diminishes T-cell mediated anti-tumor immunity even during PD-1 blockade." (PMID 41020868, 2025). "However, tumor-derived immunosuppressive factors such as IL-10 and TGF-β drive CD8+ T cell dysfunction and exhaustion, facilitating immune escape." (PMID 40438103, 2025). "This suggests that IL-10 may prolong viral replication within tumor tissue, thereby enhancing direct oncolysis and potentially facilitating a more robust anti-tumor immune response." (PMID 40723208, 2025). "Research has shown that Th17 cells support tumor growth through mechanisms that include tumor cell migration and metastasis, as well as angiogenesis and regulatory T-cell recruitment, and through the release of immunosuppressive cytokines IL-10 and TGF-β." (PMID 41441899, 2025). "PD-L1+ tumor cells recruit Tregs, enhancing their immunosuppressive functions, and suppress dendritic cell maturation/antigen presentation via soluble factors (e.g., IL-10), indirectly weakening antitumor immunity." (PMID 41479912, 2025). "A reduced IL-10 level may impair immune regulation and promote a pro-inflammatory milieu that facilitates tumor progression." (PMID 40958269, 2025). "Similarly to TGF-β, IL-10 can exert anti-tumor effects in limited amounts, but as tumors develop resistance, TAMs begin to overproduce IL-10." (PMID 40699676, 2025). "However, tumor cells begin to release cytokines like IL‐10 and TGFβ, recruiting monocytes from the bone marrow and stimulating their differentiation into TAMs within the TME." (PMID 40553053, 2025). "In line with J. Sun’s findings, we believe that a balanced state could indicate a favorable postoperative prognosis; our data suggest that an increase in the pro-inflammatory state (IL-6/IL-10 ratio) is a strong predictor of tumor recurrence." (PMID 40227646, 2025). "Tumor-associated macrophages (TAMs), which originate from monocytes or tissue-resident precursors, display the ability to transition between pro-inflammatory M1 and immunosuppressive M2 phenotypes influenced by cytokines such as IFN-γ, IL-4, and IL-10." (PMID 40807088, 2025). "The immunosuppressive properties of the tumor microenvironment (TME) further limit its efficacy: regulatory T cells (Tregs) suppress ferroptosis by consuming cysteine and secreting IL-10, while tumor cells escape through the Nrf2 pathway by upregulating GPX4 and FSP1." (PMID 40535125, 2025).
tumor (continued). "Components that promote immune suppression, such as regulatory T cells (Tregs), macrophages associated with tumors (TAMs), cytokines like interleukin-10 (IL-10) and transforming growth factors-beta (TGF-β), are crucial in establishing a favorable microenvironment for tumor growth." (PMID 41383623, 2025). "Furthermore, IL-10 expression in tumor-infiltrating regulatory T lymphocytes has been shown to facilitate the exhaustion of intratumoral CD8+ T cells." (PMID 41011273, 2025). "These altered tumor cells induce an upregulation of immunosuppressive cytokines such as interleukin-10 (IL-10) and Transforming Growth Factor Beta (TGF-β), as well as polarization of macrophages towards pro-tumor M2(Gc)-type and depletion of CD8+ effector memory T-cells." (PMID 40425576, 2025). "Specifically, under hypoxia stress, tumor cells secrete interleukin-10 (IL-10) and transforming growth factor-β (TGF-β) to drive M2-TAM polarization 59, and they upregulate the expression of CD39 and CD73 to generate adenosine as a toxic metabolite, which diminishes CD8+ T cell cytotoxicity." (PMID 39776799, 2025). "IL-10 is widely known for its immunosuppressive properties as it inhibits the activation and function of various immune cells, such as T cells and dendritic cells, to support tumor survival and growth." (PMID 41583453, 2025). "By week 12, both FMT groups showed a trend toward increased IL-10 levels, which may reflect a host adaptive response to ongoing tumor progression." (PMID 41614846, 2025). "However, Tregs, characterized by FOXP3 and CD25 expression, suppress anti-tumor responses through both cytokine-dependent (e.g., IL-10, TGF-β, IL-35) and contact-mediated mechanisms, dampening the activity of effector T cells, dendritic cells, and NK cells." (PMID 40660400, 2025). "CAFs might release immunosuppressive substances like transforming-growth-factor-b (TGF-β) and interleukin-10, potentially suppressing immune cell function and aiding tumor immune evasion in CRC." (PMID 40677714, 2025). "Hyperactive neutrophils may also suppress anti-tumor immune responses by secreting IL-10 and transforming growth factor-beta, which inhibit the function of T cells and NK cells, allowing tumor cells to evade immune surveillance." (PMID 39960903, 2025). "Urinary and serum IL-10 levels are biomarkers for tumor occurrence, while the IL-6 to IL-10 ratio may be a potent predictor of NMIBC recurrence." (PMID 40227644, 2025). "Furthermore, IL-10 secreted by TAMs can enhance the proliferation and function of Tregs, thereby facilitating tumor progression." (PMID 40948776, 2025). "However, in advanced disease, IL-10’s immunosuppressive effects seem to dominate and allow tumor progression." (PMID 41007766, 2025). "Additionally, FPR2 influences the tumor microenvironment by stimulating the secretion of Th2 cytokines, such as IL-4 and IL-10, which drive the polarization of macrophages into the M2 phenotype." (PMID 40330466, 2025). "Additionally, neutrophils can influence DCs to adopt a pro-tumor phenotype by promoting the secretion of immunosuppressive cytokines like IL-10 and IL-4, further dampening anti-tumor immunity." (PMID 40486614, 2025). "They incessantly secrete a diverse array of immunosuppressive factors, such as transforming growth factor-β (TGF-β) and interleukin-10 (IL-10), further suppressing the activity and function of immune cells, rendering it arduous for immunotherapy to fully exert its efficacious anti-tumor effect." (PMID 40230840, 2025). "Clark and colleagues reported that Streptococcus pneumoniae increases IL-10 production from NK cells in the lung and restricts host defense (IL-10 is a well-known anti-inflammatory cytokine and tumor suppressor that eradicates tumor cells and enhances antitumor immune surveillance)." (PMID 40770084, 2025). "Furthermore, to explore the possible mechanism of IL-10 attenuating the killing effect of CAP on tumor cells, the relevant signaling pathways regulated by IL-10 were detected." (PMID 41145470, 2025).